TSC2 (TSC complex subunit 2)
Diseases named in the same sentence as TSC2 in open-access papers (continued):
Sharing a sentence is not in itself a finding about the gene and the disease.
Cognitive impairment (14 papers, 2013 to 2025). Abnormal cognition is characterized by deficits in thinking, reasoning, or remembering. "TSC1 and TSC2 proteins form a complex that inhibits mTOR activity; therefore, deletion of these proteins causes hyperactive mTOR signaling, intellectual impairment, refractory epilepsy, intellectual impairment, and an autistic-like phenotype." (PMID 39845785, 2024). "We are here using a conventional Tsc2+/− model in a longitudinal setting to study onset of cognitive impairment and link it to underlying molecular changes." (PMID 39192595, 2024). "Mouse models with mutations in Tsc1 or Tsc2 exhibit a phenotypic profile similar to human patients, including cognitive impairments." (PMID 39192595, 2024). "Two probes are found in a CpG island in the body of TSC2, which has been shown to be required for mTOR signaling in the brain, which has been associated with cognitive impairment." (PMID 24373378, 2013). "The entirety of observed brain malformations, cellular aberrations, and impairments of neuroplasticity suggests cognitive deficits to be present in the Tsc2+/− Eker rat." (PMID 40611277, 2025). "To study the disease processes that lead to cognitive impairment, we have used a conventional mouse model carrying a heterozygous deletion in the Tsc2 gene in a longitudinal behavioral analysis focusing on cognitive performance." (PMID 39192595, 2024). "Its widespread use in the diagnosis of conditions including cognitive impairment has led to the detection of TSC1 and TSC2 variants in patients with less obvious clinical features and no family history of the disease." (PMID 38373162, 2024). "As cognitive impairments in TS patients develop over time, we performed a longitudinal analysis in Tsc2+/− males, using cohorts at 3–4 and 8–10 months of age." (PMID 39192595, 2024). "Both of the TSC1 or TSC2 KO mice are embryonic lethal; however, mice harboring TSC1 or TSC2 heterozygous mutations display synaptic dysfunction and cognitive impairments." (PMID 29209173, 2017). "Consistent with this, cognitive impairments of the two animal models are corrected by drugs that modulate mGluR5 in the opposite manner (CDPPB for Tsc2+/− mice and MPEP for Fmr1−/y mice)." (PMID 23935565, 2013). "Interestingly, TSC2-deficient mice that are seizure- and lesion-free do not display cognitive impairment supporting the possibility suggested by some that cognitive deficits in individuals with ASD might be caused or potentiated by seizure-induced damage." (PMID 41149794, 2025). "Because, other than in models carrying mutations in Tsc1, in models with Tsc2 aberrations, epilepsy is not found and not even predisposition to hyperexcitability is seen at early postnatal stages, this model allowed studying the occurrence of cognitive impairment independent of epileptic potential." (PMID 39192595, 2024). "We conjecture that abnormal TSC1 and TSC2 expression in these specific brain regions during critical developmental periods may affect key molecular pathways, result in measurable morphologic changes, and contribute to the cognitive impairment observed in a subset of the TSC population." (PMID 30190613, 2018). "Injection of IGF2, a molecule that induces mTOR signaling, could fully rescue cognitive impairment and IEG expression in aging Tsc2+/− animals." (PMID 39192595, 2024). "However, we did not detect cognitive impairment in infantile, adolescent or young adult Tsc2+/− animals." (PMID 39192595, 2024).
cyst (12 papers, 2012 to 2024). A sac-like closed membranous structure that may be empty or contain fluid or amorphous material. "The majority of AML/cyst-positive patients had a TSC2 mutation (51.7%), with only 10.8% having a TSC1 mutation." (PMID 39027368, 2024). "Several studies have confirmed that cyst-like tubers are more prevalent in patients with TSC2 mutations." (PMID 37232723, 2023). "Of note, cyst-like cortical tubers have been strongly associated with TSC2 gene mutations and a more aggressive seizure phenotype." (PMID 35096710, 2021). "Nevertheless, TSC1 demonstrated better cyst-free survival (median 16.9 years) than TSC2 (median 9.1 years) at any time." (PMID 38832977, 2024). "TFEB was primarily localized in the nucleus of the cyst lining cells from kidneys of Tsc2 KO (KspCre+; Tsc2fl/fl) mice and was relocalized outside of the nucleus upon this short-term Rapamycin treatment, consistent with our in vitro data." (PMID 38195686, 2024). "Type C tubers correspond to cyst-like tubers, which are found in about 50% of TSC cases at an early age and are more common with TSC2 mutations." (PMID 37232723, 2023). "The first studies examining the identity of cells lining the cysts in TSC came from heterozygote Tsc2 (Tsc2+/−) mice, which showed a predominance of IC cells within the cyst epithelia." (PMID 38028758, 2023). "Cyst formation occurred with a frequency of ~4.7 cysts/well for TSC2−/− cultures, compared with 0 and ~0.5 cysts/well for TSC2+/+ and TSC2+/− cultures, respectively." (PMID 34764250, 2021). "This is in contrast to a recent study showing that Dermo1-mediated Tsc2 ablation led to cyst formation." (PMID 30696882, 2019). "The distribution of LTL staining, representing polarity of brush borders, revealed another aspect of TSC cystic disease, namely loss of cell polarity in the single-cell proximal tubule stretches of cyst lining, in contrast to the polarized cells observed in TSC2+/− tubules." (PMID 34764250, 2021). "In contrast, the rapamycin-treated mouse tumors were almost entirely cystic, and the cyst-lining cells had a flattened appearance in comparison to tumor cells from the other four cohorts, as has been noted previously in rapamycin or RAD001 treated Tsc2+/− mice." (PMID 22363765, 2012). "The reduction in these pro‐angiogenic and pro‐tumoral factors could ameliorate the effects of TSC2‐ cells on their microenvironment, thus rapamycin may not only shrink TSC cyst and tumour size but also reduce the microenvironmental support for growth." (PMID 37337371, 2023).
hepatocellular carcinoma (12 papers, 2016 to 2025). A malignant tumor that arises from hepatocytes. "Human hepatocellular carcinomas (HCCs) with inactive Tsc2 mutations exhibit more aggressive tumor behavior in patients, and Tsc2 mutation-bearing HCCs are more sensitive to rapamycin in patient-derived tumor xenograft models." (PMID 37653030, 2023). "Deficient TSC1 or TSC2 is also observed in hepatocellular carcinoma (HCC) and bladder cancer." (PMID 35805935, 2022). "Similarly, in SNU-886, a hepatocellular carcinoma cell line with natural TSC2 loss, abemaciclib was unable to suppress S6 phosphorylation." (PMID 32391118, 2020). "The three TSC2 null liver carcinoma cell lines SNU-886, SNU-878, and SNU-398 were uniformly sensitive to GSK461364, a PLK1 inhibitor, while in contrast the TSC1 null cell lines PEER and CAL-72 were not sensitive at all with IC50 values ranging from 5 to 33 nM." (PMID 33891611, 2021). "To date, several studies have shown that TIPE1 can inhibit the activation of Rac1, its downstream target p65, and the c-Jun N-terminal kinase pathway in hepatocellular carcinoma cells and decrease mTOR phosphorylation by stabilizing TSC2 protein in a Parkinson's disease model." (PMID 31179241, 2019). "After a round of screening followed by repeat assessment using probes for each exon of TSC1 and TSC2, the osteosarcoma cell line CAL-72 showed homozygous deletion of exons 6 to 23 of TSC1; and the hepatocellular carcinoma cell line SNU-398 showed homozygous deletion of exons 10–41 of TSC2." (PMID 33891611, 2021). "Additionally, stemness genes, such as Nanog, Sox2, and Oct4, were expressed in EpCAM-positive HCC cells and TSC2-AKT signaling activated upon Sorafenib treatment, further exacerbating hepatocellular carcinoma progression." (PMID 32466488, 2020). "Through transcriptome sequencing of human hepatocellular carcinoma (HCC) samples, six genes—TSC1, TSC2, PABPC3, HIF1α, RB1CC1 (ATG17), and RPS6KA3 (RSK2)—were found to be associated with HBV infection." (PMID 33059752, 2020).
pancreatic neuroendocrine tumor (12 papers, 2014 to 2025). Pancreatic endocrine tumor, also known as pancreatic neuroendocrine tumor (PNET), describes a group of endocrine tumors originating in the pancreas that are usually indolent and benign, but may have the potential to be malignant. "Mutation and loss of function of TSC1 and/or TSC2 have also been shown to occur consistently in a variety of sporadic cancers including bladder, kidney, pancreatic neuroendocrine tumors, and PEComa." (PMID 33891611, 2021). "Mutations of genes of the mTOR pathway, such as PTEN, TSC2 and PIK3CA, have been detected in about 16% of sporadic pancreatic NETs." (PMID 39199391, 2024). "Hallmarks of NET G1/G2 are loss of chromosome 18, inactivation of CDKN1/APC, and gain of chromosomes 4, 5, and 14 in NET of the small intestine and inactivation of MEN1/chromosome 11, DAXX/ATR, and PTEN/TSC2 in pancreatic NET." (PMID 33228231, 2020). "In an analysis of gene expression profiles of 72 primary pancreatic NETs, TSC2 and PTEN were found to be downregulated in most of the primary tumors [27•]." (PMID 25092520, 2014). "A gene expression profile study of sporadic pancreatic NETs revealed down regulation of TSC2 and PTEN, two key inhibitors of the AKT/mTOR pathway in most of the sporadic NETs." (PMID 24626055, 2014). "However, there are confirmed cases of TSC2 gene LOH with pancreatic neuroendocrine tumors accompanying TSC." (PMID 25889454, 2015). "Additionally, although low expression of PTEN, TSC1, and TSC2 have been found in pancreatic NETs, TSC1 and TSC2 expression appear preserved in small intestinal NET [29•]." (PMID 25092520, 2014). "Additionally, chromosomal changes, including loss of 16p, the region containing TSC2, and loss of 10q, which contains PTEN, have been reported in pancreatic NET." (PMID 25092520, 2014). "And it has been preclinically showed that deficiency of TSC2 or PTEN expression induces impaired PI3K/Akt/mTOR activation, suggesting that mTOR overexpression with the loss of PTEN plays a key role in the development and progression of pancreatic neuroendocrine tumors." (PMID 29642873, 2018). "Pancreatic NETs frequently exhibit changes in genes such as MEN1, DAXX, ATRX, TSC1, TSC2, CDKN1A, and CDKN1B, along with alterations in CDKN2A and SETD2 in metastatic lesions." (PMID 41426335, 2025). "Pancreatic NETs have variations in DAXX, ATRX, PTEN, and TSC2, whereas GI-NETs have identified CDKN1B and RASSF1A as the recurrent mutations." (PMID 29255447, 2017). "Pancreatic NETs have a decrease in PTEN expression in 50% of patients, and a downregulation of TSC2 in 35% of patients, both of which correlate with poor survival." (PMID 29255447, 2017).
sarcoma (12 papers, 2016 to 2025). A usually aggressive malignant neoplasm of the soft tissue or bone. "TSC2 mutations, which are common across several sarcoma types, were detected in 2 (22%) of the sarcoma cases." (PMID 36426653, 2023). "Additionally, a third patient initially diagnosed with sarcoma NOS was identified as having PEComa due to TSC2 loss and was recommended treatment with an mTOR inhibitor." (PMID 38228904, 2024). "In this study, we show that PrlR levels are increased in a mouse sarcoma cell line treated with TSC2 siRNA." (PMID 26765535, 2016). "In a TSC2 (+/-) mouse sarcoma cell line, down-regulation of TSC2 using siRNA resulted in increased levels of the Prl receptor." (PMID 26765535, 2016). "We found that IS still inhibited mTORC1 signaling in TSC2 knockdown sarcoma U2OS cells as indicated by the reduction of p-S6K (Thr389), p-S6 (Ser235/236) and p-4E-BP1 (Ser65), indicating that IS inhibited mTORC1 signaling mainly through TSC2-independent pathway." (PMID 27056897, 2016).
Angiofibroma (11 papers, 2014 to 2026). A benign neoplasm of fibrous tissue in which there are numerous small and large, frequently dilated, vascular channels. "The TSC natural history database disclosed a significant association between TSC2 mutation and angiofibromas." (PMID 38658236, 2024). "For P14, analysis of an angiofibroma led to identification of three mutations in TSC2 at AF from 1.3% to 8.9%." (PMID 26540169, 2015). "For P42, an angiofibroma was found to have both an indel (c.4530_4537delTGGCGACG) and a missense (p.L590R) mutation in TSC2 at 4.6% and 2.7% AF, respectively." (PMID 26540169, 2015). "A germline mutation of the TSC1 or TSC2 gene, leading to activation of the mammalian target of rapamycin (mTOR) pathway, accounts for the pathogenesis of TSC-associated angiofibromas." (PMID 24558502, 2014). "An inactivating TSC2 c.1331del, p.(Asn444Thrfs∗5) variant (VAF 3%) was identified in genomic DNA isolated from the angiofibroma but was absent from genomic DNA isolated from blood and is, therefore, likely to be a lesion-specific, second-hit mutation." (PMID 40225170, 2023). "The authors did not observe a difference in the number of angiofibromas, which could be due to the low number of patients with a TSC1 mutation, although there appears to be a trend of increasing numbers of angiofibromas in the presence of a TSC2 gene mutation." (PMID 38658236, 2024).
lung carcinoma (11 papers, 2014 to 2022). "Tuberous sclerosis complex subunit 1 (TSC1) and 2 (TSC2) are frequently mutated in non–small cell lung cancer (NSCLC), however, their effects on antitumor immunity remained unexplored." (PMID 35119931, 2022). "The deficiency of TSC2 showed up-regulation of PD-L1 in human lung cancer cell lines." (PMID 35887000, 2022). "Furthermore, we found that loss of TSC2 up-regulated the PD-L1 of lung cancer cells at the transcriptional level." (PMID 35119931, 2022). "Different genes located on the 16p13.3 locus were hypothesized to be implicated in the poor prognosis: in lung cancer TSC2 was brought forward, in pancreatic cancer PDPK1." (PMID 26222184, 2015). "Hence, we used a KP murine syngeneic lung cancer model to test the hypothesis that Tsc2-deficient tumor was more sensitive to immunotherapy." (PMID 35119931, 2022). "To confirm the findings of in vitro CRISPR screening, we transfected lung cancer cell lines with individual sgRNAs of Tsc1 or Tsc2." (PMID 35119931, 2022). "Through in vitro and in vivo CRISPR screening in a KP lung cancer model, we identified Tsc1 and Tsc2 as regulators of antitumor immunity and sensitivity to ICB therapy." (PMID 35119931, 2022). "TSC1 and TSC2 are also potent regulators of the expression of a transmembrane protein named Programmed cell death ligand 1 (PD-L1), a target of inhibitors in non–small cell lung cancer treatment." (PMID 35887000, 2022). "Another study reported LOH for hamartin or TSC2 in 22% of 86 specimens, but none of the 80 lung cancer lines studied showed lack of expression or complete loss of either hamartin or TSC2." (PMID 24593867, 2014). "Notably, LOH for the TSC1 or TSC2 locus has been described in 22% of 86 human lung cancer specimens." (PMID 24593867, 2014). "Autophagy-inhibitor mefloquine was shown to enhance nelfinavir-mediated cytotoxicity in breast cancer (MCF7), colon cancer (HCT116), lung cancer (NCI-H460), and Tsc2−/− cells." (PMID 33228205, 2020). "MAC increased the phosphorylation of AMPK and tuberous sclerosis complex 2 (TSC2), an AMPK downstream regulator, in a time‐dependent manner in lung cancer cells." (PMID 30338933, 2018). "We next used Western blotting to determine how the phosphorylation of ACC, TSC2, and mTOR correlate with the phosphorylation of AMPK after transfection with vectors (wild-type PKR, mutant PKR, and Luc) in H1299, A549, and H322 lung cancer cells." (PMID 25798539, 2015). "Another study also reported LOH for hamartin or TSC2 in 22% of 86 specimens, but none of the 80 lung cancer lines studied." (PMID 24593867, 2014). "The expression levels of PI3-K, PI3-P, AKT, TSC2, mTOR, p70S6K and 4E-BP1 were minimally affected by the wortmannin, perifosine, or rapamycin plus T4 treatments, but their phosphorylated products were greatly affected in A549 lung cancer cells and slightly affected in A549/DDP lung cancer cells." (PMID 28969040, 2017). "A widely used anti-malarial drug chloroquine is an inhibitor of late-stage autophagy and has been used in combination with nelfinavir to demonstrate enhanced cytotoxicity in chronic lymphocytic leukemic cells, tuberous sclerosis negative (Tsc2−/−) MEF cells, and human lung cancer cells (NCI-H460)." (PMID 33228205, 2020).
facial angiofibromas (10 papers, 2008 to 2024). "In another study, children at age of two years with a TSC1 gene mutation had less hypomelanotic macules and facial angiofibromas than those with a TSC2 genetic alteration." (PMID 38658236, 2024). "Compared with individuals with TSC1 pathogenic variants, individuals with TSC2 pathogenic variants were first diagnosed at a younger age (p = 0.003) and had more retinal hamartomas (p = 0.003) and facial angiofibromas (p = 0.027) (age ≥ 3 years)." (PMID 32211034, 2020). "Patients with TSC2 variants were first diagnosed at a younger age (p = 0.003) and had more retinal hamartomas (p = 0.003) and facial angiofibromas (p = 0.027) (age ≥ 3 years) than individuals with TSC1 variants." (PMID 32211034, 2020). "Patients with TSC2 variants were identified at a younger age (p = 0.003) and showed more retinal hamartomas and facial angiofibromas compared with patients with TSC1 variants (age ≥ 3 years) (p = 0.027)." (PMID 32211034, 2020). "A more severe neurological phenotype may be associated with TSC2 mutation, while skin lesions and genotype association appear more variable among studies, except for facial angiofibromas." (PMID 38658236, 2024). "The mean grade of facial angiofibroma appears to be higher in patients with a TSC2 than TSC1 alteration." (PMID 38658236, 2024). "The presence of TSC2 mutations and most other TSC-related manifestations was significantly higher in patients with facial angiofibroma." (PMID 36104799, 2022). "Tuberous sclerosis complex (TSC) is a neurogenetic syndrome due to loss-of-function mutations in TSC2 or TSC1, characterized by tumors at multiple body sites, including facial angiofibroma (FAF)." (PMID 35358092, 2022). "Regarding facial angiofibroma (AF), the frequency of scores of 3 tended to be higher in TSC2 patients, and a statistically significant difference was obtained in those ≥10 years of age." (PMID 36232477, 2022). "Adenoma sebaceum is part of the classical triad of tuberous sclerosis (adenoma sebaceum, mental retardation and epilepsy), which is an autosomal dominant neurocutaneous disease resulting from the mutation of TSC-1 or TSC-2." (PMID 20525327, 2010). "It is likely that activated mTOR is also present in some TSC skin lesions because loss of heterozygosity for TSC2 has been demonstrated in a facial angiofibroma and tuberin and/or hamartin are absent in many facial angiofibromas from individuals with TSC." (PMID 18226258, 2008). "In patients with vs. without facial angiofibroma, TSC2 mutation (38.9% vs. 34.8%) was more common than TSC1 mutation (12.3% vs. 18.1%), and the incidence rate of most of the other TSC-related manifestations was significantly higher in patients with facial angiofibroma." (PMID 36104799, 2022).